SCIRT (stem cell inhibitory RNA transcript)
Synonyms: DATOC-1; AL109615.3
Gene: Long non-coding RNA gene on chromosome 6 (43,931,505 to 44,074,685, reverse strand). Ensembl gene ENSG00000237686.
Diseases named in the same sentence as SCIRT in open-access papers:
SCIRT is named in the same sentence as 6 diseases in open-access papers, as found by Europe PMC text mining. Sharing a sentence is not in itself a finding about the gene and the disease. The quoted sentences say what the papers report.
breast carcinoma (2 papers, 2021 to 2022). "Although SCIRT is upregulated during the tumorigenesis of breast cancer, it suppresses the cancer cell self-renewal mechanism by counteracting EZH2 and SOX2 to suppress cancer progression." (PMID 34742341, 2021). "SCIRT plays critical roles in breast cancer, where it counteracts EZH2 and SOX2 to suppresses cancer cell self-renewal mechanism, thereby inhibiting cancer progression." (PMID 34742341, 2021). "SCIRT (Stem Cell Inhibitory RNA Transcript) is a lncRNA which plays a role in transcriptional regulation of self-renewal and cell cycle-related genes important in transition between breast cancer stem cells and mature cancer cells characterized by higher proliferation rate." (PMID 36429127, 2022).
atherosclerosis (1 paper, 2021). A disease characterized by the build-up of fatty material and calcium deposition in the arterial wall resulting in partial or complete occlusion of the arterial lumen. "The results showed that SCIRT was significantly downregulated in atherosclerosis (p < 0.01), while miR-146a was significantly upregulated in atherosclerosis (p < 0.01)." (PMID 34742341, 2021). "Therefore, SCIRT is downregulated in atherosclerosis and it suppresses the proliferation of HAOSMCs by sponging miR-146a in cytoplasm." (PMID 34742341, 2021). "We showed that SCIRT is downregulated in atherosclerosis and it may sponge miR-146a to suppress the proliferation of HAOSMCs." (PMID 34742341, 2021). "In conclusion, SCIRT is downregulated in atherosclerosis and its overexpression may suppress the proliferation of HAOSMCs possibly by sponging miR-146a in cytoplasm." (PMID 34742341, 2021). "Therefore, accurate regulation of the expression of SCIRT at different stages of atherosclerosis may improve disease conditions." (PMID 34742341, 2021). "Pearson correlation coefficient analysis revealed that the expression of SCIRT and miR-146a were not correlated across atherosclerosis and control samples." (PMID 34742341, 2021).
lung carcinoma (1 paper, 2021). "Our findings suggest that the exosomal transferring of miR-665 and SCIRT is a functional and mechanism-driven pathway that contributes to cancer progression and, thus, may provide novel diagnostic and therapeutic targets for lung cancer." (PMID 34349799, 2021). "We found that miR-665 and SCIRT were significantly upregulated in lung cancer plasma exosomes, and both of them showed increased expression in metastatic patient samples." (PMID 34349799, 2021). "In addition, we found that miR-665 and SCIRT were significantly upregulated in tumor tissue and plasma of patients with lung cancer, and both of them showed increased expression in metastatic disease samples." (PMID 34349799, 2021). "In addition, we identified that plasma exosomal miR-665 and SCIRT are significantly upregulated in lung cancer patients and correlated with the advanced stage of the disease, therefore indicating a diagnostic and prognostic potential of the regulatory pathway." (PMID 34349799, 2021).
cancer (4 papers, 2021 to 2022). A tumor composed of atypical neoplastic, often pleomorphic cells that invade other tissues. "SCIRT has been characterized as a key player in cancer biology, while its role in other human diseases is unclear." (PMID 34742341, 2021). "SCIRT was reported to play a crucial role in cancer cell state transitions by direct interaction with chromatin modifier EZH2, then inhibiting cancer cells' self-renewal process." (PMID 34349799, 2021). "That SCIRT isupregulated in more aggressive cancers, and the TIC subset, is unusual, and suggests thatthe orchestration of transcriptional events during the cell state transition may leave cellsunviable if it proceeds too quickly." (PMID 34095349, 2021). "Our findings that SCIRT might promote the selective sorting of critical exo-miRNAs into cancer cell exosomes further extend our understanding of its role in tumorigenesis." (PMID 34349799, 2021).
tumor (4 papers, 2021 to 2023). "Knockdown and overexpression assays revealed SCIRT’s role as a tumor suppressor; it can restrain stemness in vitro, and tumor formation in mice." (PMID 35788171, 2022). "Among the top 20 significantly upregulated lncRNAs in the HR-treated vs. control group, SCIRT, a reported tumor repressor, exhibited the highest angiogenesis correlation score." (PMID 35698607, 2022). "Furthermore, the authors identified a novel lncRNA called SCIRT (Stem Cell Inhibitory RNA Transcript), which is strongly upregulated during tumor sphere formation, but unexpectedly counteracts stemness." (PMID 36768150, 2023).
SCIRT also shares sentences with these, for which no sentence is quoted: metastatic disease (1 paper).